ENSG00000261069 (novel transcript, SNORD host)
Gene: Long non-coding RNA gene on chromosome 15 (25,087,661 to 25,088,896, forward strand). Ensembl gene ENSG00000261069.
Gene Ontology:
Biological process: RNA processing
Cellular component: nucleolus